KCNA1 (potassium voltage-gated channel subfamily A member 1)
Description:
Voltage-gated potassium channel that mediates transmembrane potassium transport in excitable membranes, primarily in the brain and the central nervous system, but also in the kidney. Contributes to the regulation of the membrane potential and nerve signaling, and prevents neuronal hyperexcitability. Forms tetrameric potassium-selective channels through which potassium ions pass in accordance with their electrochemical gradient. The channel alternates between opened and closed conformations in response to the voltage difference across the membrane. Can form functional homotetrameric channels and heterotetrameric channels that contain variable proportions of KCNA1, KCNA2, KCNA4, KCNA5, KCNA6, KCNA7, and possibly other family members as well; channel properties depend on the type of alpha subunits that are part of the channel. Channel properties are modulated by cytoplasmic beta subunits that regulate the subcellular location of the alpha subunits and promote rapid inactivation of delayed rectifier potassium channels. In vivo, membranes probably contain a mixture of heteromeric potassium channel complexes, making it difficult to assign currents observed in intact tissues to any particular potassium channel family member. Homotetrameric KCNA1 forms a delayed-rectifier potassium channel that opens in response to membrane depolarization, followed by slow spontaneous channel closure. In contrast, a heterotetrameric channel formed by KCNA1 and KCNA4 shows rapid inactivation. Regulates neuronal excitability in hippocampus, especially in mossy fibers and medial perforant path axons, preventing neuronal hyperexcitability. Response to toxins that are selective for KCNA1, respectively for KCNA2, suggests that heteromeric potassium channels composed of both KCNA1 and KCNA2 play a role in pacemaking and regulate the output of deep cerebellar nuclear neurons (By similarity). May function as down-stream effector for G protein-coupled receptors and inhibit GABAergic inputs to basolateral amygdala neurons (By similarity). May contribute to the regulation of neurotransmitter release, such as gamma-aminobutyric acid (GABA) release (By similarity). Plays a role in regulating the generation of action potentials and preventing hyperexcitability in myelinated axons of the vagus nerve, and thereby contributes to the regulation of heart contraction (By similarity). Required for normal neuromuscular responses. Regulates the frequency of neuronal action potential firing in response to mechanical stimuli, and plays a role in the perception of pain caused by mechanical stimuli, but does not play a role in the perception of pain due to heat stimuli (By similarity). Required for normal responses to auditory stimuli and precise location of sound sources, but not for sound perception (By similarity). The use of toxins that block specific channels suggest that it contributes to the regulation of the axonal release of the neurotransmitter dopamine (By similarity). Required for normal postnatal brain development and normal proliferation of neuronal precursor cells in the brain (By similarity). Plays a role in the reabsorption of Mg(2+) in the distal convoluted tubules in the kidney and in magnesium ion homeostasis, probably via its effect on the membrane potential.
Synonyms: Kv1.1; RBK1; HUK1; MBK1; AEMK; EA1; HBK1; MK1
Tractability: Small molecule: an approved drug acts on it; it belongs to a druggable protein family. Antibody: UniProt places it where antibodies can reach, with high confidence; its Gene Ontology location is reachable by antibodies, with high confidence; UniProt predicts a signal peptide or a membrane-spanning region. PROTAC: a small molecule that binds it is known.
Target class: Potassium channels; Ion channel; Voltage-gated ion channel; Voltage-gated potassium channel
Gene: Protein-coding gene on chromosome 12 (4,909,905 to 4,918,256, forward strand). Ensembl gene ENSG00000111262.
Subcellular location: Cell membrane; Membrane; Cell projection, axon; Cytoplasmic vesicle; Perikaryon; Endoplasmic reticulum; Cell projection, dendrite; Cell junction; Synapse; Presynaptic cell membrane; Presynapse
Pathways (Reactome):
Neuronal System: Voltage gated Potassium channels
Gene Ontology:
Molecular function: delayed rectifier potassium channel activity; disordered domain specific binding; protein binding; voltage-gated potassium channel activity; monoatomic ion channel activity
Biological process: magnesium ion homeostasis; membrane repolarization during action potential; neuromuscular process; potassium ion transmembrane transport; regulation of membrane potential; action potential; cell communication by electrical coupling; cellular response to magnesium ion; detection of mechanical stimulus involved in sensory perception of pain; detection of mechanical stimulus involved in sensory perception of touch; neuronal action potential; neuronal signal transduction; regulation of muscle contraction; brain development; hippocampus development; monoatomic ion transport; neuroblast proliferation; potassium ion transport; protein homooligomerization; startle response; transmembrane transport
Cellular component: cytoplasmic vesicle; juxtaparanode region of axon; membrane; paranode region of axon; plasma membrane; voltage-gated potassium channel complex; anchoring junction; axon terminus; cell junction; cytosol; dendrite; endoplasmic reticulum; neuronal cell body; perikaryon; presynapse; presynaptic membrane; synapse; axon; axon initial segment; cell surface
Genetic constraint (gnomAD): Loss-of-function variants: 19 observed, 29.83 expected, observed/expected ratio (o/e) 0.64, 90% interval 0.44 to 0.94. The upper end of that interval is the gene's LOEUF score, 0.94, which puts it in group 3 of 6, group 1 being the genes least tolerant of losing a copy. Missense variants: 419 observed, 699.69 expected, observed/expected ratio (o/e) 0.6, 90% interval 0.55 to 0.65. Synonymous variants: 311 observed, 290.63 expected, observed/expected ratio (o/e) 1.07, 90% interval 0.98 to 1.17.
Gene-disease validity (ClinGen):
ClinGen rates the evidence that KCNA1 causes each of these diseases.
episodic ataxia type 1 (autosomal dominant): Definitive.
Homologues: Orthologues: chimpanzee KCNA1 (99% identical), macaque KCNA1 (99% identical), dog KCNA1 (99% identical), mouse Kcna1 (98% identical), pig KCNA1 (98% identical), rat Kcna1 (98% identical), guinea pig KCNA1 (98% identical), rabbit KCNA1 (96% identical), tropical clawed frog kcna1 (90% identical), zebrafish kcna1a (86% identical), zebrafish kcna1b (83% identical). Paralogues in human: KCNA2 (79% identical), KCNA3 (75% identical), KCNA4 (69% identical), KCNA5 (67% identical), KCNA6 (65% identical), KCNA10 (60% identical), KCNA7 (57% identical), KCNC4 (37% identical), KCNC3 (37% identical), KCNC2 (36% identical), KCND1 (35% identical), and 19 more.
Diseases named in the same sentence as KCNA1 in open-access papers:
KCNA1 is named in the same sentence as 120 diseases in open-access papers, as found by Europe PMC text mining. Sharing a sentence is not in itself a finding about the gene and the disease. The quoted sentences say what the papers report.
epilepsy (95 papers, 2005 to 2026). A brain disorder characterized by episodes of abnormally increased neuronal discharge resulting in transient episodes of sensory or motor neurological dysfunction, or psychic dysfunction. "Shaker mammalian homologs and its complex role places Drosophila in a strong position as a model system to study neurocardiac channelopathies, such as those caused by KCNA1 mutations, long QT syndromes, and sudden unexplained death in epilepsy (SUDEP)." (PMID 41548155, 2026). "Mutations in the Kv1.1 (Kcna1) subunit of voltage-gated potassium channels cause significant brain damage and neurodegeneration in epilepsy, with direct implications for SUDEP." (PMID 40867142, 2025). "Immunohistochemistry in healthy mice shows that the RTN expresses the Kv1.1 protein, suggesting that it is a substrate for the epilepsy-related Kcna1 mutation, potentially affecting its excitability." (PMID 40004062, 2025). "Mutations and abnormal functions of KCNA1/Kv1.1 channels can lead to changes in neuronal excitability, leading to epilepsy and other neurological disorders in humans." (PMID 41155561, 2025). "Mutations in the KCNA1 gene (encoding Kv1.1) cause a variety of human diseases, including epilepsy and episodic ataxia type 1 (EA1)." (PMID 41151066, 2025). "The Kcna1 gene encodes pore-forming Kv1.1 voltage-gated potassium channel α-subunits and has direct genetic relevance for human epilepsy and SUDEP." (PMID 39822954, 2025). "Complete knockout mice exhibit severe temporal lobe seizures and premature death, while conditional models with neuron-specific deletion of Kcna1 are associated with epilepsy, premature death, and cardiorespiratory dysregulation." (PMID 41151066, 2025). "A similar loss of function effect as KCNA1 for the corresponding substitution P405L in Kv1.2 was found in several patients with severe drug-resistant epilepsy." (PMID 39434833, 2024). "The mammalian orthologs of these genes, especially DVL2 and KCNA1/2, are implicated in epilepsy and episodic ataxia which are associated with both glutamate excitotoxicity and hippocampal based cognitive deficits." (PMID 37351153, 2023). "A previous study of KCNA1 mutations discovered that most of the variants related to epilepsy or seizures occur in the protein’s pore domain, comprising the S5, S6, and S5–S6 linker domains." (PMID 37240170, 2023). "Overall, approximately two-thirds of all known KCNA1 mutations that cause epilepsy or seizures localize to the S5–S6 pore domain region of Kv1.1." (PMID 37240170, 2023). "Previous analyses of human KCNA1 variants have shown that epilepsy-linked mutations tend to cluster in regions critical for the channel’s pore, whereas EA1-associated mutations are evenly distributed across the length of the protein." (PMID 37240170, 2023). "The third most common phenotype associated with KCNA1 variants is epilepsy or seizures, accounting for approximately 32% of mutations." (PMID 37240170, 2023). "Analysis of the percentage of total epilepsy- or seizure-related KCNA1 mutations by protein domain reveals that variants in S5–S6 are nearly twice as likely (43–100%) to cause epilepsy as mutations anywhere else in the protein (0–38%)." (PMID 37240170, 2023). "We previously demonstrated that reducing Scn8a expression is therapeutic in Scn1a+/− mice and in mice with epilepsy caused by loss of the potassium channel genes Kcna1 and Kcnq2." (PMID 37901435, 2023). "The newly described KCNA1 variants further support this initial genotype–phenotype association by strengthening the correlation between mutations in the pore domain and epilepsy." (PMID 37240170, 2023). "These recent studies in mice add to the growing list of genetic modifiers that can significantly alter phenotypes associated with epilepsy due to Kcna1 mutation." (PMID 37240170, 2023).
epilepsy (continued). "Since then, mutations in KCNA1 have been associated with a wide variety of other diseases including epilepsy, hypomagnesemia, paroxysmal movement disorders, hyperthermia, and combinations of these pathologies." (PMID 37240170, 2023). "The prolines of the PVP motif have an especially strong association with a risk of epilepsy as all four of the KCNA1 missense mutations that affect these residues cause epilepsy." (PMID 37240170, 2023). "Epilepsy is more common in EA1 patients than the general population implicating KCNA1 as a cause of epilepsy." (PMID 37008993, 2023). "In an analysis of 47 pathogenic KCNA1 mutations, EA-1 associated variants occur along the whole length of the protein, whereas epilepsy-related variants tend to cluster in the S1/S2 transmembrane domains and pore region of Kv1.1." (PMID 37008993, 2023). "Two new KCNA1 variants (L296F and G396R) were recently discovered with links to epilepsy and breathing difficulties, suggesting a previously unrecognized connection between KCNA1 channelopathy and respiratory phenotypes, especially in epilepsy patients." (PMID 37240170, 2023). "Among the eight recently identified epilepsy- or seizure-related mutations in KCNA1, four reside in S5–S6 (G336E, G376S, G396R, and P403A), strengthening the association between mutations in the pore domain and epilepsy or seizures." (PMID 37240170, 2023). "The P264LfsTer10 mutation is reminiscent of the megencephaly (mceph) mouse model of Kcna1, which has epilepsy due to an 11-nucleotide deletion causing a frameshift that truncates the Kv1.1 protein at amino acid 230 in the S2 domain." (PMID 37240170, 2023). "These new variants broaden the scope of known pathogenic functional and molecular changes in KCNA1 that can cause epilepsy." (PMID 37240170, 2023). "We also found that Kcna1, which has been implicated to be involved in epilepsy, was highly upregulated in DAPK1-KO mice." (PMID 37047515, 2023). "Two KCNA1 variants have been identified in epilepsy patients with breathing issues occurring specifically at night or during sleep." (PMID 37240170, 2023). "We have recently identified a de novo variant in KCNA1 in the highly conserved Pro-Val-Pro motif within the pore of the Kv1.1 channel in a girl affected by early onset epilepsy, ataxia and developmental delay." (PMID 35897654, 2022). "Interneuronal cells derived from MGE were transplanted in the transgenic mouse model of channelopathy associated with epilepsy that presents loss-of-function of a Shaker-like potassium channel Kv1.1/Kcna1." (PMID 35250498, 2022). "So far, epilepsy seems less likely to occur because of the KCNA1 mutation with respect to EA1, requiring perhaps more deleterious defects of Kv1.1 activity, and less frequent de novo modifications and recessive inheritance have been reported." (PMID 35897654, 2022). "KCNA1 variants are typically associated with episodic ataxia type 1, and have in rare cases been associated with paroxysmal dyskinesia and epilepsy." (PMID 35457207, 2022). "The selective deletion of KCNA1 in neurons causes epilepsy, premature death, and cardiorespiratory dysregulation in mice." (PMID 34208776, 2021). "This work investigates how two ion channel mutations, one associated with autism (Scn2a‐null) and one with epilepsy (Kcna1‐null), interact to modify genotype–phenotype relationships in the context of autism." (PMID 33484493, 2021). "This work investigated how two ion channel mutations, one associated with autism (Scn2a‐null) and one with epilepsy (Kcna1‐null), interact to modify genotype–phenotype relationships in the context of autism." (PMID 33484493, 2021). "KCNA1 mutations associated with epilepsy tend to cluster in the S1/S2 helices and pore domain of the channel." (PMID 33833732, 2021). "Up to 10% of patients with EA1 suffer from epilepsy, and myokymia and hyperthermia have been reported to co-occur in KCNA1 mutation carriers as well." (PMID 34305802, 2021).
epilepsy (continued). "This work also sheds light on the complexity of ASD–epilepsy comorbidity, showing that epilepsy‐associated mutations (such as Kcna1 deletion) can produce epileptic or autistic phenotypes depending on gene dosage." (PMID 33484493, 2021). "Why are all KCNA1 variants associated with epilepsy limited to the S1 and S2 helices in the voltage-sensing domain and to the pore domain?" (PMID 32316562, 2020). "Kv1.1 impairment associated with epilepsy has been shown also in other animal models of epilepsy carrying defects in the KCNA1 gene." (PMID 32331416, 2020). "Although EA1 is the most common diagnosis resulting from a KCNA1 mutation, patients can also exhibit many other types of diseases such as epilepsy, hypomagnesemia, and paroxysmal kinesigenic dyskinesia (PKD)." (PMID 32316562, 2020). "In support of this, several gene mutations that modify epilepsy phenotypes in Kcna1-null mice have been identified." (PMID 32316562, 2020). "Since that time, KCNA1 mutations have also been associated with several other diseases, including epilepsy and hypomagnesemia." (PMID 32316562, 2020). "At least two nearby KCNA1 variants (p.Val408Met and p.Val408Leu) have also been associated with variable cognitive impairment and epilepsy." (PMID 32705822, 2020). "As for now, epilepsy seems less likely to occur as a consequence of KCNA1 mutation with respect to episodic ataxia, as less frequent de novo modifications and recessive inheritance have been reported." (PMID 32331416, 2020). "Although all pathogenic KCNA1 mutations identified result in channel LOF, do the epilepsy-associated mutations impair Kv1.1 function more severely?" (PMID 32316562, 2020). "As Kcna1 dysfunction is known to cause diseases of the brain (epilepsy, ataxia) and kidney (hypomagnesemia), it makes sense that Kv1.1 subunits in other regions of the body play individually critical roles." (PMID 32316562, 2020). "In patients with KCNA1-related epilepsy, three mutations have been identified in the S1 and S2 helices of the voltage-sensing domain." (PMID 32316562, 2020). "As far as new cases of Kv1.1 epileptic mutations will be reported, it would be interesting to unravel the specific genetic and functional mechanisms that bring a KCNA1 mutation to cause either EA1 or epilepsy or mixed phenotypes in patients." (PMID 32331416, 2020). "Several epilepsy and seizure-associated mutations (P403S, P405S, P405L, and V408L) are caused by underlying nucleotide changes in the region of the KCNA1 mRNA transcript that is edited by ADAR2." (PMID 32316562, 2020). "Mutations in the KCNA1 gene, which encodes Kv1.1, are associated with the neurological diseases episodic ataxia and epilepsy." (PMID 31250689, 2019). "Kcna1 mutations were first found to cause epilepsy in mice which led to their discovery in human epilepsy patients." (PMID 31250689, 2019). "The epilepsy phenotype associated with Kcna1 mutations represents an illustrative example of successful bench-to-bedside scientific discovery." (PMID 31250689, 2019). "About a year after the initial discovery that Kcna1 deletion causes epilepsy in mice, the first patients were identified with epilepsy due to KCNA1 loss-of-function missense mutations." (PMID 31250689, 2019). "RBPs regulate mRNA distribution and protein synthesis of known epilepsy targets such as CaMKIIα or KCNA1 encoding for the potassium channel Kv1.1, as well as multiple other ion channels." (PMID 27855659, 2016). "The subsequent genetic analysis revealed that the individuals displaying epilepsy carried the F184C mutation in their KCNA1 gene that profoundly altered the channel's properties." (PMID 24062639, 2013). "Even more noteworthy, epilepsy can occur with mutations/changes in KCNA1 by both LOF and GOF." (PMID 41155561, 2025). "Similarly, KCNA1 mutations, which impair potassium ion flow, can be provoked early after-depolarizations and arrhythmias, which affect both epilepsy and non-epilepsy populations." (PMID 40867142, 2025).